CDK6 (cyclin dependent kinase 6)
Diseases named in the same sentence as CDK6 in open-access papers (continued):
Sharing a sentence is not in itself a finding about the gene and the disease.
acute myeloid leukemia (23 papers, 2012 to 2025). Acute myeloid leukemia (AML) is a group of neoplasms arising from precursor cells committed to the myeloid cell-line differentiation. "Hematologic malignancies such as acute myeloid leukemia (AML) and T-cell lymphoblastic lymphoma can be caused by CDK6 dysfunction." (PMID 35780240, 2022). "This dependency results in a high vulnerability toward inhibitors of CDK4 and CDK6 and suggests new avenues for therapeutic intervention against acute myeloid leukemia." (PMID 33217477, 2021). "Compound 25c was previously synthesized by Brand and co-workers and studied for its ability to selectively degrade CDK6 over CDK4, in particular the correlation between the use of the CDK6 degrader in acute myeloid leukemia cells was investigated." (PMID 33803309, 2021). "Notably, the previous studies indicated that CDK6 expression was absolutely upregulated in patients with de novo Acute Myeloid Leukemia (AML) compared to healthy individuals." (PMID 40076203, 2025). "The activity of the CDK4/CDK6/Cyclin D complex is increased in acute myeloid leukemia." (PMID 27323399, 2016). "CDK6 is frequently upregulated in hematopoietic tumors and plays a critical role in acute myeloid leukemia (AML) and acute lymphoblastic leukemia." (PMID 39593745, 2024). "Similarly, in acute myeloid leukemia (AML) the efficacy of CDK6-targeted degrader is also impaired by p18INK4c and p16INK4a." (PMID 38561743, 2024). "In line with this, CDK6 inhibition reduced the activity of MAP-ERK and PI3K/AKT/mTOR signaling pathways in an acute myeloid leukemia cell line." (PMID 36619863, 2022). "Previous studies demonstrated that Sox4, RasGRP1, RasGRP3, IGF1R, CDK6, and LEF1 are the key oncogenes/tumor suppressor genes in acute myeloid leukemia." (PMID 31242922, 2019). "Moreover, CDK6 can be effectively degraded, and the proliferation of the tumor cells can be inhibited in CDK6-dependent and CKD4-independent acute myeloid leukemia cells." (PMID 36557960, 2022). "The combination of therapy with a CDK6 inhibitor (palbociclib) and ATRA (tretinoin) could be an alternative approach for the treatment of acute myeloid leukemia (AML)." (PMID 38731835, 2024). "Additionally, ABBV-075 downregulates MYC, CDK6, and BCLxL expression, upregulates p21 and BIM expression, and induces apoptosis in acute myeloid leukemia (AML) cells." (PMID 38539460, 2024).
neuroblastoma (23 papers, 2011 to 2025). Neuroblastoma (NB) is the most common solid, extracranial childhood tumor. "Recent in vitro and in vivo studies on the therapeutic utility of inhibitors targeting the cyclin D1-associated kinases CDK4/CDK6 revealed promising results in various cancer types including neuroblastoma." (PMID 29719597, 2018). "An analogous point mutation in Cdk6 that blocks the interaction of p16INK4a with CDK6 has also been reported in a human neuroblastoma cell line." (PMID 36051751, 2022). "Overexpression of CDK4 or CDK6 conferred expected resistance in neuroblastoma cells to palbociclib, as shown by colony formation and EC50 shift." (PMID 34893606, 2021). "While Rb1 loss is very rare in neuroblastoma, several studies have shown that the cyclin D/CDK4/CDK6 pathway is hyperactive in neuroblastoma." (PMID 34893606, 2021). "The main characteristics of the Group 4α tumors are the v-myc avian myelocytomatosis viral-related oncogene, neuroblastoma-derived (MYCN) and cyclin dependent kinase 6 (CDK6) amplifications, 8p loss and 7q gain." (PMID 29932116, 2018). "Several cell cycle regulators, especially those within the cyclin D1/CDK4/CDK6/RB pathway, are hyperactive in neuroblastoma." (PMID 29719597, 2018). "We propose that miRNA-124 triggers a CDK6-dependent decrease in cell proliferation, which facilitates the establishment of MV persistence in neuroblastoma cells." (PMID 29073265, 2017). "Here, we provide evidence that expression of miRNA-124 in neuroblastoma cells is an important molecular link between MV persistent infection, CDK6 inhibition, and reduced cell division that facilitates establishment of persistent infection." (PMID 29073265, 2017). "We propose that miRNA-124 limits CDK6 expression which in turn results in decreased cell proliferation, facilitating the establishment of MV persistence in neuroblastoma cells." (PMID 29073265, 2017). "We propose that MV persistent infection is facilitated by the down-regulation of CDK6 by miRNA-124 in neuroblastoma cells." (PMID 29073265, 2017). "Western blot analysis showed that G9a knockdown also led to a marked down-regulation of CyclinD1, CDK4 and CDK6 in the three neuroblastoma cell lines." (PMID 25198515, 2014). "Thus, transfection of neuroblastoma cells with miR-124 results in a decrease in cell proliferation and an increase in apoptosis, which is in concordance with the downregulation of CDK6 by miR-124." (PMID 22123030, 2011). "miRNA appeared to be downregulated in neuroblastoma cell lines due to promoter methylation, but treatments with 5′azacitidine increased miRNA expression and led to malignancy decrease through downregulation of miRNAs’ targets such as CDK6, DNMT3B, E2F3, OLFM3, and IFNAR1." (PMID 34832966, 2021). "Furthermore, although overexpression or dysregulated function of cdk6 has been implicated in several types of cancer, including lymphoid malignancies, squamous cell carcinomas, and neuroblastomas, levels of cdk6 are decreased in many breast tumors and most breast tumor-derived cell lines." (PMID 24848372, 2014). "The decrease in PCLAF gene expression significantly downregulated CyclinA2, CyclinB1, CyclinD1, CyclinE2, CDK2, and CDK6, which further showed that downregulation of PCLAF can inhibit the proliferation of neuroblastoma." (PMID 35210406, 2022). "MV persistence infection of a human neuroblastoma cell line (UKF-NB-MV), exhibit high miRNA-124 expression, and reduced expression of cyclin dependent kinase 6 (CDK6), a known target of miRNA-124, resulting in slower cell division but not cell death." (PMID 29073265, 2017). "Dual inhibition of CDK4/CDK6 by LEE011 is reported to cause cell cycle arrest and induces senescence in 12 out of 17 neuroblastoma cell lines, but not all the tested cell lines were sensitive to LEE01127." (PMID 27378523, 2016).
neuroblastoma (continued). "Additionally, Moqidem suggested that cell death induced by A. vulgaris on SH-SY5Y human neuroblastoma cell line was through apoptosis induction accompanied by significant downregulation of the cell cycle genes (CDK4, CDK6 and E2F3), and upregulation of the tumor suppressor gene PTEN." (PMID 36015443, 2022). "Interestingly, CDK4, rather than CDK6, is essential for the proliferation of adult oligodendrocyte progenitor cells, and knockdown of CDK4 in neuroblastoma cells reduces their proliferation." (PMID 34625907, 2022).
lung adenocarcinoma (20 papers, 2014 to 2025). A carcinoma that arises from the lung and is characterized by the presence of malignant glandular epithelial cells. "Yu and colleagues identified CDK6 as one of the mRNAs differentially expressed in lung adenocarcinoma (LUAD) and lung squamous cell carcinoma (LUSC) through mRNA and circRNA expression patterns comparison." (PMID 39944826, 2025). "In lung adenocarcinoma cells downregulating CDK6 inhibited the proliferation rate and stimulated G0/G1 arrest." (PMID 37529110, 2023). "GPR37 belongs to the G protein-coupled receptor family, and GPR37 can induce lung adenocarcinoma cell cycle arrest in G1 phase by binding to CDK6, thereby enhancing the progression and migration of lung adenocarcinoma cells." (PMID 36712848, 2022). "The mechanism was revealed to inhibit CDK4/CDK6-cyclinD1 complex by increasing p21 expression in colorectal cells, and upregulate p21 expression level in lung adenocarcinoma cells." (PMID 34122110, 2021). "The results indicated that the expression of oncoprotein TRIM59 positively correlates with Cyclin CDK6 expression in Wang cell line 2 (A549 cells) and Lee Lung (lung adenocarcinoma and squamous cell lung carcinoma tissue)." (PMID 30515965, 2019). "The results indicated that dried apricot polyphenols (DAPs) could cause cell cycle arrest in the G0/G1 and G2/M phases by decreasing the cyclin D1, CDK4, cyclin B1, CDK1, and CDK6 levels in A549 human lung adenocarcinoma cells." (PMID 39796398, 2025). "In addition to BLCA, high transcriptional CDK6 mRNA also predicts poor prognosis in pancreatic adenocarcinoma, adrenocortical adenocarcinoma, uterine corpus endometrial carcinoma, lung adenocarcinoma, low-grade glioma, mesothelioma, and sarcoma from TCGA database analyzed using the UALCAN website." (PMID 35463324, 2022). "Herein, we report that Leucine-rich pentatricopeptide repeat-containing (LRPPRC) protein can form a positive feedback loop with CDK6 to regulate CDK6 expression and CDK4/6i treatment response in lung adenocarcinoma (LUAD)." (PMID 37452037, 2023). "Forced over-expression of miR-186 in lung adenocarcinoma cells inhibits proliferation and invasion by targeting and inhibiting the cyclin D1, cyclin-dependent kinase 2 (CDK2), and CDK6 genes and pituitary tumor transforming gene." (PMID 25742499, 2015). "Transcriptome data from the TCGA database showed that the RNA level of LRPPRC was positively correlated with that of CDK6 (n = 515, Rho = 0.327, P < 0.0001) and E2F1 (n = 515, Rho = 0.383, P < 0.0001) in lung adenocarcinoma; and the positive correlation tendency was widespread in different tumors." (PMID 37452037, 2023).
acute lymphoblastic leukemia (19 papers, 2013 to 2025). Leukemia with an acute onset, characterized by the presence of lymphoblasts in the bone marrow and the peripheral blood. "Cyclin-dependent kinase 6 (CDK6) encodes a regulator of G1/S cell-cycle progression and has been found rearranged in B-cell lymphoma (IGK/CDK6), chronic lymphocytic leukemia (IGL/CDK6, IGH/CDK6, IGK/CDK6), and acute lymphoblastic leukemia (CDK6/MLL)." (PMID 23637631, 2013). "In a model for p185BCR-ABL+ B-acute lymphoid leukemia, we show that CDK6 is part of a transcription complex that induces the expression of the tumor suppressor p16INK4a and the pro-angiogenic factor VEGF-A." (PMID 23948297, 2013). "In contrast, overexpression and chromosomal translocation of CDK6 is observed in acute lymphoblastic leukemia (ALL) and lymphoma." (PMID 34065376, 2021). "By analyzing 40 different types of the human cancer cell lines in the CCLE database, the expression of CDK6 was found to be highly expressed in both acute lymphoblastic leukemia (ALL) and AML cell lines." (PMID 33597968, 2020). "A recent publication indicated an inverse correlation between CDK6 and the prominent glucose transporter GLUT3/SLC2A3 expression levels in acute lymphoid leukemia patient samples." (PMID 39966356, 2025). "This includes a pro-survival activity of cyclin D3/Cdk6 activity attributed to its phosphorylation and inhibition of glycolytic enzymes, phosphofructokinase (PFKP) and PKM2, in T acute lymphoblastic leukemia (T-ALL) cells and other tumors with high expression of Cdk6." (PMID 35670764, 2022). "Notably, CDK6 exerts its functions in both kinase-dependent and -independent manners, and only its kinase-independent function is required for the growth of Philadelphia-positive acute lymphoblastic leukemia (Ph+-ALL)." (PMID 35410300, 2022). "CDK6 is also involved in hematopoietic malignancies such as Mixed-Lineage Leukemia (MLL) related AML and acute lymphoblastic leukemia (ALL)." (PMID 36120561, 2022).
esophageal cancer (17 papers, 2012 to 2025). A primary or metastatic malignant neoplasm involving the esophagus. "Another study has verified that the progression of esophageal cancer was promoted by XIST-regulated miR-494/CDK6 axis to activate the JAK2/STAT3 signal pathway." (PMID 32127028, 2020). "By blocking YAP1 and CDK6 with the YAP1 inhibitor CA3, and the CDK6 inhibitor LEE001 significantly suppressed esophageal cancer cell growth and CSC properties, particularly in radiation-resistant cells in both OAC and OSCC." (PMID 33665161, 2020). "Aberrant activation of the Cyclin D1-CDK4/6-Rb signaling pathway is common in ESCC, suggesting that CDK6 amplification promoting the progress of aggressive type of esophageal cancer." (PMID 32662828, 2020). "Induction of YAP1 expression in esophageal cancer cells up-regulated CDK6 expression, increased transcription, and consequently induced the resistance against radiotherapy." (PMID 33665161, 2020). "Recently, an experimental study suggested that CDK6 upregulation resulting in inhibition of human esophageal epithelial cell apoptosis might involve in the etiological mechanism of Cd-induced esophageal cancer." (PMID 35252173, 2022). "A recent study demonstrated the abnormal expression of XIST could contribute to esophageal cancer via miR-494/CDK6 axis." (PMID 32038997, 2019). "And by analyzing the CDK6 expression in esophageal PDX model and transfecting esophageal cancer cell line with small interfering RNA, we found that the CDK6 expressions may be a useful marker to identify the patients who are more likely to benefit from treatment with SHR6390." (PMID 29370817, 2018). "For example, in esophageal cancer cells, YAP promoted CDK6 transcription and expression, leading to radiation resistance, whereas CDK6 knockdown abrogated YAP-mediated radiation resistance." (PMID 40693409, 2025). "CDK1/2 overexpression has been reported in CRC and esophageal cancers, CDK4 overexpression has been described in most types of GI tumors and CDK6 overexpression has been observed in CRC and esophageal cancers." (PMID 34503239, 2021). "Copy number abnormalities of MET, CDK6 and EGFR were also observed in esophageal cancer tissues." (PMID 34944989, 2021).
multiple myeloma (17 papers, 2011 to 2025). "These analyses reveal a CDK6-governed protein resistance signature that includes myeloma high-risk factors such as TRIP13 and RRM1." (PMID 35197447, 2022). "Our recent work has implicated the cyclin-dependent kinase 6 (CDK6) / retinoblastoma (Rb) axis in the mechanism by which FOXM1 promotes myeloma." (PMID 30463534, 2018). "Recently, CDK6 upregulation has been observed in multiple myeloma patients refractory to lenalidomide treatment." (PMID 37872167, 2023). "Overexpression of CDK6 in multiple myeloma cell lines reduces sensitivity to IMiDs while CDK6 inhibition by palbociclib or CDK6 degradation by proteolysis targeting chimeras (PROTACs) is highly synergistic with IMiDs in vitro and in vivo." (PMID 35197447, 2022). "Cells cultured in the presence of 100 nM lenalidomide for several weeks had enhanced levels of CDK6 protein and were partially resistant to lenalidomide, highly consistent with the findings in lenalidomide-treated myeloma patients." (PMID 35197447, 2022). "This work identifies CDK6 upregulation as a druggable target in IMiD-resistant multiple myeloma and highlights the use of proteomic studies to uncover non-genetic resistance mechanisms in cancer." (PMID 35197447, 2022). "Given that CDK6 upregulation was found in lenalidomide-resistant patients and induced expression reduced lenalidomide-sensitivity, we next tested the effects of the CDK6 inhibitor palbociclib in multiple myeloma cell lines." (PMID 35197447, 2022). "Here we applied an integrated proteomics and transcriptomics approach in primary multiple myeloma matched pre-treatment/resistant samples that identified and validated a targetable CDK6 governed protein resistance signature." (PMID 35197447, 2022). "This, as well as the exact downstream functions of CDK6 in resistant multiple myeloma, needs to be evaluated in detail in future studies." (PMID 35197447, 2022). "Consistent with the results for the kinase inhibitor palbociclib, PROTAC-mediated CDK6 degradation reduced multiple myeloma cell growth in a subset of cell lines." (PMID 35197447, 2022). "Here, we show that combining CDK6 inhibition with IMiDs is particularly synergistic in multiple myeloma." (PMID 35197447, 2022). "Myeloma cells treated with 50 μM etomoxir exhibited a significant but modest reduction in the protein levels of cyclin D2 and CDK6." (PMID 23029529, 2012). "In conclusion, our results identify CDK6 as a master regulator in treatment-resistant relapsed multiple myeloma and provide a strong rationale for further investigating CDK6 inhibition together with IMiDs in multiple myeloma." (PMID 35197447, 2022). "Treatment of 5-Aza-2′-deoxycytidine led to miR-124-1 demethylation and re-expression of mature miR-124, which also associated with emergence of euchromatic trimethyl H3K4 and consequent downregulation of CDK6 in myeloma cells harboring homozygous miR-124-1 methylation." (PMID 21544199, 2011). "This issue could be overcome by either hijacking two different E3 ligases, CRBN and VHL, or a PROTAC, such as YKL-06-102, that simultaneously targets IKZF1, IKZF3, and CDK6, achieving intramolecular synergistic effects even in IMiD-insensitive multiple myeloma cells." (PMID 35197447, 2022). "In addition to cyclin D overexpression, increased Cdk4 and Cdk6 are also described in myeloma." (PMID 29163849, 2017). "Furthermore, recent work indicates that PD033299, which selectively inhibits CDK6, might be efficacious against multiple myeloma and MLL-rearranged AML, malignancies where the pre-leukemic cell of origin is thought to be an HSC." (PMID 25704240, 2015). "In aggregate, these data imply that high CDK6 and RRM1 expression selectively reduce IMiD sensitivity in multiple myeloma cell lines." (PMID 35197447, 2022). "We found that CDK6 overexpression reduces sensitivity to IMiDs, but not to other drugs in multiple myeloma." (PMID 35197447, 2022).
multiple myeloma (continued). "Here, we apply quantitative proteomic analyses in paired, longitudinal primary multiple myeloma samples and identify CDK6 upregulation as a non-genetic resistance mechansim for IMiDs in multiple myeloma that can be overcome by pharmacologic intervention." (PMID 35197447, 2022). "Our data imply that the effects of CDK6 in multiple myeloma depend on its kinase function but are independent of RB1, the CDK4/6 substrate which is most relevant for other cancers." (PMID 35197447, 2022). "Likewise, myeloma cells treated with 20 μM orlistat exhibited a significant reduction in p21 and phospho-pRb levels in myeloma cells, whereas cyclin D1, cyclin D2, cyclin E, CDK4, CDK6, p16 and p27 remained unchanged." (PMID 23029529, 2012). "Of note, CCND2 myeloma cells overexpress CDK6 and CDK4 while CCND1 myeloma cells overexpress CDK4 but not CDK6, suggesting that CDK4 is “empty” of cyclin D in CCND2 myeloma cells." (PMID 30545397, 2018). "For example, in multiple myeloma cells, APRIL promotes cell cycle progression in cyclin D2-positive cells by upregulating CDK4, CDK6, and phospho-retinoblastoma protein, but did not regulated cell-cycle proteins in cyclin D1-positive cells." (PMID 25826583, 2015).